BRAF (B-Raf proto-oncogene, serine/threonine kinase)
Diseases named in the same sentence as BRAF in open-access papers (continued):
Sharing a sentence is not in itself a finding about the gene and the disease.
melanoma (continued). "However, we further reveal that the dysfunction of ARNT contributed to the metastasis of BRAF V600E-mutated melanoma cells." (PMID 33446631, 2021). "The second strategy uses BRAF (V-Raf murine sarcoma viral oncogene homolog B1) and MEK (Mitogen-activated protein kinase kinase) inhibitors to block the mitogen-associated protein kinase (MAPK) pathway that is constitutively activated by BRAF V600 mutations in 45% of melanoma patients." (PMID 34445175, 2021). "BRAF is one of the most important proto-oncogenes in humans and about 8% of human tumors have BRAF mutations, of which the vast majority are BRAF-V600E mutation and mainly occur in melanoma, colon cancer and thyroid cancer." (PMID 34249939, 2021). "In light of the relatively high mutation rate of KIT in cutaneous melanoma and since BRAF, KIT, and NRAS mutations appear to be mutually exclusive, the screening of KIT mutations, at least in exons 9/11/13, is suggested in BRAF/NRAS double-wild-type melanoma patients." (PMID 34123788, 2021). "Studies on vemurafenib, a signaling inhibitor that targets an oncogenic BRAF mutation common in melanoma, suggested that cell-to-cell variation in drug resistance, measured by long-term proliferation, originates from epigenetic differences in gene expression that pre-exist treatment." (PMID 34326399, 2021). "While a higher tumour burden and lower TILs has previously been shown to be associated with poor response to immunotherapy, our study is the first to demonstrate that these factors, in addition to a BRAF mutation, also discriminate rapid progressors from other progressors in melanoma." (PMID 34202352, 2021). "Reanalysis of a published dataset (GSE98314) revealed that treatment with the BRAFi Dabrafenib decreased EZH2 expression in 11 different BRAF mutated melanoma cell lines and we found a significant inverse correlation of EZH2 and miR-129 expression (r = −0.46; p = 0.029)." (PMID 34063443, 2021). "For instance, vemurafenib is a targeted therapy for melanoma with BRAF gene mutation." (PMID 33390784, 2021). "However, a higher proportion of patients with BRAF-mutated melanoma were enrolled in the CheckMate 037 and 067 studies than in the present study." (PMID 34115870, 2021). "It was also shown that following hypoxia exposure, melanoma cells bearing BRAF V600E mutation exhibit downregulation in the expression of genes encoding apoptotic regulators—BAD (Bcl-2-associated agonist of cell death) and BCL2L1 (Bcl-2-like 1, also known as Bcl-X)." (PMID 33918883, 2021). "It has been shown that more than 50% of melanomas harbor activating BRAF mutations." (PMID 34567185, 2021). "Typically, either BRAF or NRAS mutations are found in malignant melanomas." (PMID 34576054, 2021). "Although BRAF and NRAS mutations are usually mutually exclusive in melanoma patients, BRAF/NRAS dual mutation may derive from two subclonal populations." (PMID 34675197, 2021). "Since BRAF-mutated melanomas show specific histomorphological features, specific dermoscopic features could be anticipated as well." (PMID 33954019, 2021). "Somatic oncogenic mutations of BRAF are reported in approximately 50% of melanomas." (PMID 33925387, 2021). "Activating mutations in BRAF are found in 40–50% of melanomas." (PMID 33804800, 2021). "Indeed, PTEN loss promotes BRAF inhibitor resistance to melanoma by inhibiting pro-apoptotic gene Bim expression." (PMID 34282258, 2021). "The evidence herein suggests that a combination of SQ1 or SQ2 with autophagy inhibitors could be further explored to expand the efficacy of these agents and ideally enhance the targeting of BRAF mutated melanomas." (PMID 34885944, 2021). "A total of 40–50% of melanomas harbour BRAF mutations and can benefit from targeted therapy." (PMID 33562484, 2021). "Moreover, BRAF inhibitor treatment increased the TRIM16 production in melanoma cells, while TRIM16-deficient mice exhibited elevated incidence of metastasis compared to the control animals." (PMID 33430277, 2021).
melanoma (continued). "Spearman’s correlation between gene expression data of FASN and the IC50 values of PLX4720 (a structurally distinct analog of PLX4032) across BRAF-mutated melanomas indicated that FASN levels were inversely correlated with IC50 values both at gene (rs = −0.5) and protein level (rs = −0.53)." (PMID 34068792, 2021). "BRAF V600 mutations represent an early event in the development of melanoma." (PMID 34203771, 2021). "About 50% of all melanomas harbor activating BRAF mutations (over 90% V600E)." (PMID 34526609, 2021). "Previous studies have shown that cfDNA testing may be a surrogate for determining BRAF mutations in patients with melanoma." (PMID 34298804, 2021). "Therefore, determining BRAF mutational status in melanoma patients helps clinicians determine the first line of treatment." (PMID 34944799, 2021). "Therefore, the aim of this study was to evaluate the utility of CT-based radiomics to predict BRAF mutation status (mutant versus wild type) in melanoma lung metastases." (PMID 33915880, 2021). "It is unknown whether a low dose of BRAF-inhibitor can mitigate the skin toxicity associated with full-dose MEK-inhibitor treatment in patients with advanced NRASQ61R/K/L mutant melanoma." (PMID 33921947, 2021). "In 2011, the Food and Drug Administration (FDA) approved vemurafenib as the first BRAF targeted therapy for unresectable or metastatic BRAF V600E-mutated melanoma based on an overall survival rate of 84%and a 63% decrease in the risk of mortality from the BRIM 3 trial." (PMID 34804979, 2021). "Around 40% of melanomas have a BRAF mutation, most frequently BRAFV600E." (PMID 34830178, 2021). "Indeed, 50% of melanoma patients present BRAF mutations, however, all responders develop resistance to the inhibitors typically within one year of treatment." (PMID 33451139, 2021). "Only 10% of lesions with dotted vessels in that study were BRAF-mutated melanomas (P = .004)." (PMID 33954019, 2021). "The overall mutation rate of BRAF in malignant tumors is 7% but varies with tumor type, and mutations are observed in approximately 50% of patients with melanoma, approximately 25% of patients with anaplastic thyroid cancer, and 2–8% of patients with non-small cell lung cancer." (PMID 33622273, 2021). "Overall, one could state that BRAF-mutated melanoma patients may indeed benefit of an additional treatment opportunity represented by the targeted therapies." (PMID 34073232, 2021). "For example, if a BRAF p.V600E mutation is present at 3% allele frequency in the DNA sequence of a low tumor cellularity melanoma sample, if it is also present in the cDNA sequence, it may be reported with more confidence." (PMID 34093633, 2021). "D594G, G469A and K601E are the frequently observed BRAF variants in mucosal melanomas." (PMID 34571863, 2021). "In addition, oncogenic mutations in BRAF, an oncoprotein, has been found in melanoma, thyroid cancer, and colorectal cancers." (PMID 33808717, 2021). "Selective BRAF inhibitors (BRAFis), such as vemurafenib, have been approved for clinical use and significantly improved the progression-free survival (PFS) and overall survival (OS) of patients with melanoma carrying BRAF mutations compared with the traditional chemotherapy dacarbazine." (PMID 34512348, 2021). "Overall, about 35–50% of melanomas of all clinical types have mutations in the V600 codon of BRAF." (PMID 34680222, 2021). "This may possibly explain why upregulated RTK signaling can mediate BRAF inhibitor resistance through pathway reactivation in melanoma cells, even though the activating mutation under treatment is BRAFV600E." (PMID 33947959, 2021). "The lower effect of targeted therapy (TT) was due to selection or to more aggressive features in BRAF mutated patients, or could be related to the immune mechanism involved in the initial elimination of melanoma." (PMID 33747946, 2021).
melanoma (continued). "The clinical efficacy of the “one-two-punch” hypothesis is currently evaluated with vorinostat treatment in patients with resistant BRAF V600E mutated advanced melanoma, and the results will hopefully prove that the concept is clinically relevant." (PMID 33525637, 2021). "BRAF mutational status fills a pivotal role in the management of both advanced and completely resected melanoma patients; thus, special attention should be addressed to the detection of BRAF mutations, with the aim of avoiding the risk and under-treatment of false-negative cases." (PMID 33801689, 2021). "Furthermore, DCA potentiates the effect of vemurafenib on only BRAF-mutated melanoma cells through a cooperative attenuation of energy production as it was identified by means of OCR/ECAR measurements." (PMID 33730175, 2021). "However, BRAF mutation in melanoma, especially BRAFV600 mutations, activates the downstream pathway of MAPK and positively drives the development of malignant melanoma." (PMID 34829495, 2021). "In UV-related melanoma evolution the primary events depend on the age of the individual and the biological demeanor of the oncogenic initiating mutation in the nevi, such as BRAF." (PMID 35127523, 2021). "We first assessed the RICTOR expression in melanocytes and BRAF-mutated melanoma by Western blot." (PMID 34680615, 2021). "In BRAFV600E melanoma cells, ER stress-induced autophagy by fenretinide or bortezomib, inhibitors of mTORC signaling or of the proteasome respectively, was elicited to a significantly lesser extent than in non-BRAF-mutated melanoma." (PMID 34298710, 2021). "Similarly, in completely resected stage III BRAF-mutated melanoma, an adjuvant combination of dabrafenib and trametinib resulted in a significantly lower risk of recurrence compared to the adjuvant use of a placebo." (PMID 33562484, 2021). "BRAF tyrosine kinase inhibitors (TKIs) have been successfully used in people with cutaneous melanoma, but due to the low frequency of BRAF mutation in mucosal melanoma, TKIs are rarely effective in this type of melanoma." (PMID 35053051, 2021). "Frequently reported features of melanoma found to be associated with BRAF mutation status." (PMID 34068774, 2021). "The first successful treatment for BRAF mutation was vemurafenib in melanoma." (PMID 35145907, 2021). "Conversely, in non- BRAF-mutated melanomas, novel combination strategies are still highly needed." (PMID 33918490, 2021). "Approximately 25.5% of melanomas in Chinese patients harbor BRAF V600 mutations." (PMID 34201096, 2021). "BRAF gene mutations exist in papillary thyroid cancer, malignant melanoma and colorectal cancer." (PMID 33622273, 2021). "Inactivation of PTEN is often found in advanced melanoma and is coincident with BRAF mutation." (PMID 34282258, 2021). "Acquired resistance to conventional melanoma therapies (either targeted- or immuno- therapy) caused by various bypass signaling activation mechanisms, leads to limited efficacy of currently available BRAF inhibitors, vemurafenib and PLX8394." (PMID 33917428, 2021). "Moreover, CAFs devoid of β-catenin exhibited reduced ERK (extracellular signal-regulated kinase)/MAPK and PI3K/AKT signaling, as well as blocked EMT in BRAF-mutated melanoma cells." (PMID 33430277, 2021). "It is well-established that the mitogen-activated protein kinase (MAPK) and phosphatidylinositol 3-kinase (PI3K)/protein kinase B (AKT) signaling pathways are overactivated in melanoma since BRAF mutation leads to uncontrollable cell growth and ultimately develops into cancer." (PMID 33841154, 2021). "It has been reported that BRAF mutation could inactivate the antitumor immune response by upregulating the MAPK signaling pathway in melanoma." (PMID 34249711, 2021).
melanoma (continued). "In about 40–50% of patients, melanoma cells are characterized by a mutation of BRAF (v-rat fibrosarcoma (Raf) murine sarcoma viral oncogene homolog B) at position 600 (BRAFV600), which results in constitutive activation of the extracellular signal-regulated kinase (ERK) pathway." (PMID 34576054, 2021). "For instance, only patients with a BRAFV600E-mutated melanoma are expected to benefit from targeted therapies with BRAF/mitogen-activated protein kinase (MEK) inhibitors, while patients with a BRAFK601E-positive melanoma respond only to a minority of those drugs, such as trametinib." (PMID 34123788, 2021). "A combination of TMB, inflammatory gene expression signature, and BRAF mutation status may predict response to immune checkpoint blockade in advanced melanoma." (PMID 34804979, 2021). "As a reference, we used the A375 melanoma cell line that carries a BRAF V600E mutation." (PMID 33669371, 2021). "This may be consistent with the relatively high mutational burden in melanoma, and selection under conditions of BRAF inhibition may cause DNA repair stress, leading to additional driver mutations." (PMID 34831420, 2021). "Hence, the BRAF mutation status in melanoma lung metastases cannot be predicted using radiomics features or visually scored LIDC criteria." (PMID 33915880, 2021). "However, in individuals with late-stage melanoma who carry the V600E mutation, the BRAF inhibitor vemurafenib has been proven to improve survival." (PMID 35003391, 2021). "BRAF mutations represent currently the main molecular targets for melanoma treatment, as they involve approximately 50% of the cases, and identify patients who may benefit from treatment with BRAF inhibitors, like vemurafenib or dabrafenib." (PMID 34307142, 2021). "The inhibition of BRAF is the main strategy to treat melanoma patients with BRAF mutation." (PMID 33669949, 2021). "NRAS is the second most common mutated oncogenic driver in melanoma, after BRAF mutations." (PMID 35187538, 2021). "We recently showed in another study that the lack of detection of ctDNA by qPCR Cobas (Roche diagnostics) at the initiation of first-line treatment was an independent factor of good prognosis, regardless of treatment (immunotherapy or targeted therapy) in BRAF or NRAS-mutated melanoma patients." (PMID 33920470, 2021). "BRAF-mutated melanoma is aggressive and resistant to chemotherapy." (PMID 34115870, 2021). "This could have affected their results due to the predominance of thicker melanomas in the BRAF-mutated group." (PMID 33954019, 2021). "Pseudopods and radial projections were both observed more frequently in BRAF-mutated melanomas." (PMID 33954019, 2021). "The BRAF mutations are associated with decreased disease-free and melanoma-specific survival." (PMID 34105069, 2021). "Interestingly, melanomas with exclusively V600E mutation and melanomas with both V600E and V600M BRAF mutations present 7 differentially expressed mature microRNAs." (PMID 34698264, 2021). "These melanomas rarely harbor BRAF, NRAS, or NF1 mutations (triple wild-type)." (PMID 34571969, 2021). "Combining with temsirolimus, the treatment of BRAF V600E-mutated melanoma brain metastases cell lines may be effective in vitro." (PMID 34446007, 2021). "Among the gene mutations in melanoma cells, the most common is BRAF mutation (accounting for 60% of all melanomas), which could lead to disordered cell signaling pathways and uninhibited proliferation." (PMID 34582363, 2021). "First, global hypomethylation induced by or associated with the NRASQ61 driver mutation was identified as a common feature in melanoma (similar to what Hou and colleagues demonstrated for BRAF V600E signaling), potentially playing an important role in the disease pathogenesis." (PMID 34944843, 2021).
melanoma (continued). "In excess 80% of BRAF mutations detected in malignant melanoma are missense mutations, which cause the valine amino acid at position 600 to be substituted to glutamic acid (V600E); 5%-12% are valine to lysine (V600K) and less than 5% are valine to aspartic acid (V600D) or valine to arginine (V600R)." (PMID 34155457, 2021). "The authors also showed exosomal DNA could carry BRAF mutations, common mutations in malignant melanoma, and mutations in epidermal growth factor receptor (EGFR) in NSCLC." (PMID 33805398, 2021). "Furthermore, trametinib has been approved by the FDA as a monotherapy for the BRAF V600 mutation in unresectable or metastatic melanomas." (PMID 34744739, 2021). "As for vemurafenib, the efficacy of dabrafenib was further extended when combined with a MEK inhibitor (trametinib), which led to approval of dabrafenib plus trametinib, as a combinatorial agent for treating advance melanoma harboring BRAF(V600E/K) mutations in clinical therapy." (PMID 35582307, 2021). "Many melanomas are associated with activating BRAF mutation." (PMID 34063443, 2021). "While the combination of 4-MU and vemurafenib is applicable only to BRAF-mutated melanomas, combined treatment with UA and DCA might in theory be applied more broadly in cancers that rely upon glycolysis to sustain their growth." (PMID 33623106, 2021). "BRAF mutation is the most common in melanoma and occurs in 40–60% of cases." (PMID 33918490, 2021). "Furthermore, the venetoclax-S63845 combination potentiated melanoma cell killing caused by the BRAFV600E inhibitor darafenib in BRAF-mutant melanoma cells." (PMID 34331013, 2021). "NECTIN4 was shown to be frequently expressed in BRAF-mutated melanoma." (PMID 33478111, 2021). "We reported four cases of pretreated patients with BRAF-mutated advanced melanoma, who were rechallenged with off-label targeted therapy after immunotherapy with single agents (at least anti-PD-1 antibodies), as effective approved therapeutic options were not available." (PMID 34136385, 2021). "Similarly, poor response to BRAF inhibitors in patients with BRAF-mutant melanoma has been correlated to concurrent loss-of-function mutations in the PTEN gene, which can lead to the reactivation of the PI3K/AKT pathway." (PMID 34123788, 2021). "Interestingly, CUP sensitivity predicted by the trametinib signature approximates that of BRAF-mutated melanomas, while a panel of aggressive metastases from carcinomas of known origin did not display a responder signature." (PMID 33941777, 2021). "We therefore concentrated our ex vivo studies on BRAF-mutated melanoma." (PMID 34680615, 2021). "More than half of all melanomas harbor a mutation in the BRAF oncogene." (PMID 33954019, 2021). "SIJ1777 and its derivatives may serve as novel and promising BRAF inhibitors targeting melanoma cells expressing pan-class BRAF mutations." (PMID 33917428, 2021). "In melanoma, mutated BRAF is directly targetable with the drug vemurafenib, among others." (PMID 34441338, 2021). "Indeed, a selective small molecule inhibitor of BRAF has been found to sensitize patients with BRAF-mutated melanoma to achieve therapeutic efficacy." (PMID 34572136, 2021). "Additionally, MMP-1, known as pro-collagenase-1, is overexpressed in BRAF-mutated melanoma and contributes to melanoma invasion and growth by activating the ERK pathway." (PMID 33833342, 2021).